KIAA0319 (KIAA0319)
Diseases named in the same sentence as KIAA0319 in open-access papers (continued):
Sharing a sentence is not in itself a finding about the gene and the disease.
dyslexia (continued). "For instance, the European consortium NeuroDys performed a cross-linguistic case-control association study of dyslexia with data from more than 950 dyslexic individuals using targeted genotyping of selected markers in DYX1C1, DCDC2, KIAA0319, and the MRPL19/C2orf3 locus." (PMID 34068951, 2021). "KIAA0319 was found to be expressed less in individuals with a specific haplotype associated with dyslexia—variant rs9461045, later on proven to be caused by the introduction of a binding site for the transcription factor OCT1 in the KIAA0319 promoter." (PMID 28334068, 2017). "Here we explored whether variations within three related-dyslexia genes, namely KIAA0319, DCDC2, and CNTNAP, might affect cortical thickness measures in FTD patients." (PMID 27484312, 2016). "The cluster of significant effect on white matter volume for rs7619451 in the right temporo-parietal region partly overlaps with a region previously found significant for rs3743204 and rs6935076 from the dyslexia candidate genes DYX1C1and KIAA0319, respectively." (PMID 26400686, 2015). "These pieces of evidence support the fact that KIAA0319 may have a role in the development of dyslexia." (PMID 25015435, 2014). "Since ADHD and dyslexia have high comorbidity in humans, we evaluated response latency across groups to ensure that RNAi of Kiaa0319 did not also cause hyperactivity." (PMID 24871331, 2014). "Previous studies have shown that KIAA0319 is a candidate gene for dyslexia in western populations." (PMID 25015435, 2014). "In support of this, a cilia-related coexpression module derived from publically available microarray datasets found that the dyslexia associated genes, DCDC2, DYX1C1, and KIAA0319 are coexpressed in cilia, suggesting they interact with genes involved in the determination of LR asymmetry." (PMID 24068947, 2013). "In a longitudinal study of a cohort of English children, associations were observed between DCDC2 and dyslexia, and between CMIP and KIAA0319 and single-word reading and spelling across the ability range; significance was increased by inclusion of individuals with comorbid LI or ADHD." (PMID 23308072, 2012). "We identified association between reading abilities and the DCDC2, KIAA0319, and CMIP genes and have shown that these associations follow different patterns; whereas DCDC2 is associated more specifically with dyslexia, CMIP and KIAA0319 are associated with reading abilities in the normal range." (PMID 21457949, 2011). "Interestingly, they found only weak and inconsistent support for association with another gene located close to KIAA0319, namely DCDC2, which had previously been reported as also associated with dyslexia." (PMID 19338500, 2009). "AAVR shares striking homology with KIAA0319, a candidate gene that may contribute to dyslexia." (PMID 28679762, 2017). "Nevertheless, these results indicate a role for KIAA0319 and especially AU040320 in the normal development and/or function of auditory brainstem structures, and support the hypothesis that dyslexia susceptibility genes might produce specific abnormalities in central auditory processing." (PMID 29045729, 2017). "We may, therefore, reasonably conclude that KIAA0319 may not be directly associated with dyslexia in Chinese children with the Chinese language being used as the testing criteria, phonological awareness and may influence other language-based disabilities." (PMID 25015435, 2014). "They found that there are overlapping expression patterns in human dyslexia-related genes (ROBO1 and KIAA0319, and CNTNAP2 and CMIP) and the expression patterns of these genes in the marmoset brain." (PMID 37760998, 2023). "NCAN is expressed in several tissues, including several brain areas; its expression was significantly correlated with that of two other dyslexia candidate genes, namely GRIN2B and KIAA0319." (PMID 34068951, 2021).
dyslexia (continued). "The impact of altered gene expression levels on neuronal function was repeatedlyobserved for the best replicated dyslexia candidate genes (DCDC2,DYX1C1 and KIAA0319)." (PMID 29473935, 2018). "Within the three most-replicated dyslexia loci, four candidate genes for dyslexia have been identified: DYX1C1 in DYX1 on chromosome 15q21, DCDC2 and KIAA0319 in DYX2 on chromosome 6p21, and ROBO1 in DYX5 on chromosome 3p12–q12." (PMID 23308072, 2012). "The literature mining approach revealed the consensus ciliary signature to include a group of genes related to the neurological disorder dyslexia (DCDC2, DYX1C1 and KIAA0319)." (PMID 22558177, 2012). "We present additional evidence for a role in dyslexia risk for DCDC2, KIAA0319, GRIN2B and CYP19A1, but not for DNAAF4." (PMID 40424442, 2025). "These attentional tasks are not usually analyzed with dyslexia candidate genes, therefore, one intriguing result obtained from our cohort is the relationship of this type of task with KIAA0319, FOXP2 and DYX1C1 SNPs." (PMID 30379906, 2018). "Dyslexia candidate genes have been correlated with tasks measuring phonological abilities, such as DYX1C1 and FOXP2 with short-term memory or phonological memory, or DCDC2 and KIAA0319 with phoneme awareness itself." (PMID 30379906, 2018). "Interestingly, markers within KIAA0319 and FOXP2 were significantly related to dyslexia when comorbid samples were included (Dys+Com-vs-Ctr_Dys), as well as when comorbids were analyzed as an independent group (Com-vs-Ctr_Dys/Com-vs-Ctr_ADHD/Com-vs-Ctr_Com)." (PMID 30379906, 2018). "From those genes, DYX1C1, KIAA0319 and DCDC2 are the most prominent candidate genes for dyslexia." (PMID 27312598, 2016). "Kiaa0319 RNAi also duplicates corpus callosum abnormalities in dyslexia without changing body weight or the volume of the cortex and hippocampus." (PMID 24871331, 2014). "The role of dyslexia candidate genes have not been completely established, and with the exception of the KIAA0319 gene, functional molecular mechanisms have not been described to explain genetic associations." (PMID 20846247, 2011). "Our study therefore supports a developmental role for KIAA0319 which is not restricted to the brain and may contribute to the ongoing discussion around the role of neuronal migration in dyslexia." (PMID 30950042, 2019). "Thus, it is reasonable to speculate that deficits of KIAA0319 and FMR1 might give rise to dysfunction in M pathway for children with dyslexia." (PMID 25071661, 2014). "While this paper presents conceptual connections between electrophysiological antero-posterior asymmetry and dyslexia-related genes, such as DCDC2, KIAA0319, or ROBO1 this is hypothetical and not a fact due to a lack of genetic or molecular data." (PMID 40941656, 2025).
Anxiety (2 papers, 2017). Intense feelings of nervousness, tension, or panic often arise in response to interpersonal stresses. "Altered levels of KIAA0319 protein in shRNA-treated rats have been reported to affect spatial memory and auditory processing, while Kiaa0319 KO mice have only very mild deficits in anxiety-like behavior and sensorimotor gating." (PMID 29045729, 2017). "Taken together, those data suggest the possibility of subtle alterations in anxiety-related behaviour and in sensorimotor gating resulting from Kiaa0319-deletion, although further analyses with larger cohorts and/or different tests may be necessary to replicate and extend these initial results." (PMID 27510895, 2017).
language disorder (1 paper, 2011). A category of disorders characterized by an impairment in the development of an individual's language capabilities, which is in contrast to his/her non-verbal intellect. "We provide further support for the role of KIAA0319 and DCDC2 in contributing to reading abilities and novel evidence that the language-disorder candidate gene CMIP is also implicated in reading processes." (PMID 21457949, 2011).
tumour (3 papers, 2023 to 2025). "To assess the clinical relevance of NRF2 pathway activation in OAC primary tumours, we employed four NRF2 targets (KIAA0319, ARID3A, HSPA1B, PTGR1) from clusters 2 and 9 to calculate the risk score based on datasets from The Cancer Genome Atlas (TCGA)." (PMID 40473905, 2025). "Concordant increased tumour gene expression and plasma protein expression was only found for HSPA2 and KIAA0319 in the CAC group." (PMID 37045997, 2023). "Notably, the expression trends of KIAA0319, DERL1, SGK3, and CLTCL1 in tumor tissues mirrored those observed in the cell lines, providing consistency between in vitro and in vivo observations." (PMID 39792732, 2025).
genetic diseases (1 paper, 2009). "Our findings provide new insights for understanding the role of KIAA0319 in RD and brain development as well as for establishing the role of non-coding mutations in complex genetic diseases." (PMID 19325871, 2009). "More broadly, these findings are relevant for further understanding the role of KIAA0319 in RD and brain development as well as for establishing the role of non-coding mutations in complex genetic diseases." (PMID 19325871, 2009).
KIAA0319 also shares sentences with these, for which no sentence is quoted: ciliopathy (2 papers); depression (2); attention deficit-hyperactivity disorder (1); autism (1); autism spectrum disorder (1); autoimmune disease (1); Brain atrophy (1); breast carcinoma (1); childhood apraxia of speech (1); communication disorder (1); lacrimal gland lesions (1); learning disorders (1); Miscarriage (1); neurological disorder (1); Parkinson disease (1).